DAB2 (DAB adaptor protein 2)
Diseases named in the same sentence as DAB2 in open-access papers (continued):
Sharing a sentence is not in itself a finding about the gene and the disease.
tumor (continued). "Based on previous studies showing that YAP1 activation plays an important role in DAB2-regulated prometastatic activity of tumor-associated macrophages, we investigated whether H pylori activated YAP1 via DAB2." (PMID 38481347, 2024). "The pro-tumorigenic role of DAB2 may be mediated by tumour associated macrophages and requires further investigation." (PMID 37815603, 2023). "Together these findings suggest that the pro-tumorigenic roles of DAB2 may be mediated by cells in the tumour–associated stroma." (PMID 37815603, 2023). "Although the majority of literature has demonstrated either downregulation or loss of DAB2 expression in tumour tissues compared to normal tissues there are also several studies which have demonstrated an increase in DAB2 expression in cancer and an association with tumour progression." (PMID 36614139, 2022). "Loss of DAB2 expression in tumour compared to normal tissues is well documented." (PMID 36614139, 2022). "DAB2 expression was also associated with tumour progression in urothelial carcinoma." (PMID 36614139, 2022). "DAB2 exhibits tumour suppressor activity and is associated with the development of various tumours." (PMID 33166004, 2021). "Of note, M2 macrophages may promote tumor growth, and DAB2+ tumor associated macrophages have shown to play central role in lung metastasis formation, therefore would be of interest to address the role of DAB2 in myeloid cells during tumor progression." (PMID 33178208, 2020). "Several human miRNAs have been reported to target DAB2, causing tumor promotion." (PMID 32025216, 2020). "Besides, DAB2 is highly expressed in tumor-infiltrating tumor-associated macrophages." (PMID 34109210, 2021). "In addition, we studied the effects of X-ray irradiation on expression of DNMTs, Wnt pathway factors, the methylation status of the Dab2 gene, as well as associated changes in cell proliferation, invasiveness, and tumor progression by in vitro and in vivo experiments." (PMID 30547821, 2018). "In conjunction with the overproduction of TGF-β in tumor cells, the loss of Dab2 expression and subsequent impairment of receptor-dependent TGF-β depletion may contribute to the accumulation of TGF-β in the microenvironment, a scenario that correlates with poor prognosis of cancer patients." (PMID 24638085, 2014). "One study identified DAB2 (Disabled homolog 2) as a downstream target gene of miR-145 during tumor metastasis." (PMID 40689207, 2025). "The downregulation of DAB2, along with its known tumor-suppressive and immunomodulatory functions, suggests a mechanistic contribution to tumor progression in TNBC." (PMID 40565366, 2025). "DAB2 plays a role in signaling pathways involved in cell differentiation, proliferation, migration, tumor suppression and cellular homeostatic mechanisms." (PMID 41398915, 2025). "DAB2, known as a tumor suppressor and adaptor protein, is involved in TGF-β signaling, cytoskeletal regulation, and immune modulation." (PMID 40565366, 2025). "The DAB2 gene exhibited a 0.59-fold decrease between tumor and normal tissues, with a measurement of 0.67 in metastatic tissues." (PMID 40565366, 2025). "Another study showed that disabled homolog 2 mitogen-responsive phosphoprotein (DAB2) is highly expressed in tumor-infiltrating TAMs, and its gene ablation significantly impairs the formation of lung metastasis." (PMID 38693304, 2024). "Consistently, DAB2 expression was substantially higher in tumor tissues from GEO datasets (GSE27342 and GSE54129) and our cohort." (PMID 38481347, 2024). "Western blots confirmed downregulation of SRC/YAP1 and SRC/RHOA signaling axis in the DAB2 downregulation cells, and validated tumor growth inhibition of DAB2." (PMID 38481347, 2024).
tumor (continued). "This suggests that the expression of FAP and DAB2 genes is valuable in indicating the prognosis of tumor patients." (PMID 39239526, 2024). "By analyzing scRNA-seq data from 11 organs, we observed a progressive increase in the proportions of FAP+ CAFs and DAB2+ TAMs in normal (n = 25), adjacent (n = 60), and tumor (n = 220) samples." (PMID 39239526, 2024). "DAB2 functions as a tumor suppressor via its inhibition on the oncogenic signaling pathways including Wnt/β-catenin and transforming growth factor beta (TGFβ) pathways." (PMID 38481347, 2024). "DAB2+ TAMs were also found to localize to the tumor-invasive front and participate in integrin recycling, ECM remodeling, and directed migration." (PMID 39239526, 2024). "The DAB2+ and SPP1+ tumor-associated macrophages (TAMs) reinforce the function of FAP+ CAFs through signals such as TGF-β, PDGF, and ADM." (PMID 39239526, 2024). "The ratio of stromal to tumor DAB2 staining was significantly increased in metastatic compared to primary HGSOC tissue (p = 0.019)." (PMID 37815603, 2023). "Understanding the pro-tumorigenic roles of DAB2 in the surrounding tumor microenvironment needs further investigation." (PMID 37815603, 2023). "Previous studies pointed out the potential of DAB2 as a tumor suppressor gene since a decrease in DAB2 expression was observed in a wide range of tumors." (PMID 37510211, 2023). "Loss of DAB2 in cancer activates Wnt and MAPK signaling, promoting EMT, cell migration and tumor formation." (PMID 37815603, 2023). "In their modelling system, DAB2 was negatively correlated with tumor purity indicating a stronger relationship with cells in the tumor microenvironment (R = − 0.542, p = 1.74e−20)." (PMID 37815603, 2023). "Disabled homolog 2 mitogen-responsive phosphoprotein (DAB2) positive TAMs, which localized at the tumor-invasive front, promotes metastasis via matrix remodeling." (PMID 36906534, 2023). "We found a decrease in DAB2 expression in most of the CRC tumor specimens in comparison with the healthy intestinal margin extracted from the same patients." (PMID 37510211, 2023). "DAB2 expression was analyzed immunohistochemically in the tumor tissue and the colon resection margin was used as a control." (PMID 37510211, 2023). "Significant upregulation of expression is found in genes associated with tumor cell invasion such TGFβ1, ROAR, DAB2, BMP6, NOS2, PLXN2, and CADPS, whereas TCF4 was significantly downregulated in AHCY deficient cells." (PMID 38003292, 2023). "DAB2 overexpression had both tumor suppressive and promoting functions in A2780 and OVCAR3 cells, however DAB2 overexpression strongly inhibited their in vivo invasion in the chicken CAM assay." (PMID 37815603, 2023). "As a benchmark, we performed the same experiments with Dab2-edited BMDMs (editing efficiency of 67%), which are known to have an anti-tumor effect." (PMID 37388918, 2023). "In low-grade and high-grade CRC, a diminishing expression of DAB2 was observed, and this rarely presented in tumor cells or stroma." (PMID 37510211, 2023). "DAB2 (disabled-2) is highly expressed in tumor-infiltrating TAM, and its genetic ablation can significantly damage the formation of lung metastasis." (PMID 37693905, 2023). "In NSCLC cell line, LK2, x-ray irradiation promoted de-methylation of DAB2 CpG sites and enhanced DAB2 and Axin expression which inhibited Wnt signalling, cell proliferation and in vivo tumour formation." (PMID 36614139, 2022). "Dab2 promotes changes to epithelial-mesenchymal transition and increases tumor proliferation, migration, and invasion; inhibiting the protein leads to suppression of these properties and improves prognosis." (PMID 35167594, 2022). "Disabled-2 (DAB2) is considered to be an immune-regulatory factor, and has recently been found to be involved in the regulation of tumor-related signaling pathways." (PMID 35493471, 2022).
tumor (continued). "Transcriptomics of tumour associated macrophages (TAMs) has also identified a pro-metastatic role of DAB2 in the tumour microenvironment." (PMID 36614139, 2022). "In NSCLC, DAB2 expression was lost in 95% of primary tumours compared to matched normal tissues, with 85% of tumours having a higher methylation status of the DAB2 promoter." (PMID 36614139, 2022). "Re-expression of DAB2 through targeting DNA methylation presents another possible treatment mechanism in tumours where methylation downregulation occurs." (PMID 36614139, 2022). "Enrichment of pathways using data from TCGA suggested that DAB2 was relevant to some pathways that played various essential roles in the tumor growth and aggressive phenotypes such as NF-kappa B signaling pathway and PI3K-Akt signaling pathway." (PMID 37223105, 2022). "Re-expression of DAB2 in these cases should therefore be tumour suppressive and a potential treatment strategy." (PMID 36614139, 2022). "Despite most of the evidence supporting DAB2 is a tumour suppressor, some studies have found contradictory findings suggesting a tumour promoting role for DAB2." (PMID 36614139, 2022). "There is strong evidence describing the tumour suppressive function of DAB2 particularly through inhibition of key signalling pathways involved in cell survival and cell fate determination." (PMID 36614139, 2022). "Numerous studies have shown that DAB2 acts as an oncogenic factor to inhibit tumor cell proliferation in the early tumor stage, but in the late tumor stage, DAB2 promotes tumor cell EMT and invasion leading to metastasis." (PMID 35847972, 2022). "This review will cover the broad depth literature on the tumour suppressor role of DAB2, highlighting its complex relationships with different pathways." (PMID 36614139, 2022). "DAB2, initially identified as a tumour suppressor, is also an important adaptor molecule for clathrin-mediated endocytosis." (PMID 36614139, 2022). "Re-expression of DAB2 through targeting DNA methylation presents a possible treatment mechanism in tumours where methylation downregulation occurs." (PMID 36614139, 2022). "For example, we recently discovered that the disabled homolog 2 mitogen-responsive phosphoprotein (DAB2) plays a critical role in the reprogramming of pro-tumour macrophages." (PMID 34685679, 2021). "Downregulation of DAB2, which is a putative tumor suppressor and involves in the TGF-β pathway and promotes EMT, was reported in breast cancer tumors." (PMID 34801010, 2021). "In our in vivo assays, tumor-bearing athymic nude mice subcutaneously inoculated with human UCB cells (MGH-U-3 or UM-UC-3) were treated by DAB2-targeting siRNA." (PMID 31968685, 2020). "That is consistent with previous reports showing DAB2 as a putative tumor suppressor in various cancer types 21-31." (PMID 32025216, 2020). "DAB2 has been considered to be a tumor suppressor gene because DAB2 is lowly expressed in several tumor cells and is thought to inhibit tumor metastasis." (PMID 31968685, 2020). "Studies have also found that cathepsin B-mediated proteolysis of DAB2, a tumor suppressor, induces cell entry into autophagy, promotes metastasis." (PMID 33335896, 2020). "It has been reported that DAB2 can regulate tumor progression by stimulating EMT-dependent metastasis." (PMID 31968685, 2020). "To elucidate the relationship between DAB2 and tumor cells, cytokines, and the microenvironment surrounding the cancer cells, we need further experimentation." (PMID 31968685, 2020). "DAB2 has also been described as a putative tumor suppressor, as it was found downregulated in a variety of epithelial cancers." (PMID 33178208, 2020). "Our results showing lower DAB2 expression in EBV-positive GC cell lines than in EBV-negative cells support that DAB2 functions as a tumor suppressor in EBVaGC." (PMID 32025216, 2020). "Dab2 mRNA expression was found to be decreased in PDAC tumor samples, as compared to levels observed in normal pancreatic tissue." (PMID 31101868, 2019).
tumor (continued). "In line with this, Dab2 heterozygous and homozygous mice also have a slightly reduced tumor incidence." (PMID 31671891, 2019). "When stratified by tumor grade, Dab2 levels were found to be significantly higher in disease-free versus recurred/progressed disease status, with Grade 2 tumors attaining the highest significance." (PMID 31101868, 2019). "The Cox-regression model revealed low-DAB2 expression was an independent factor of poor survival (P<0.05), and also of tumor recurrence with the predictive performance superior to clinical TNM stage (P<0.05)." (PMID 27036032, 2016). "Our results found patients with low-DAB2 expression ESCCs had significantly larger tumor size, deeper tumor invasion depth, lymph node metastasis, worse survival, and higher recurrence rate (P<0.05)." (PMID 27036032, 2016). "DAB2 is a well-established tumor-suppressor and a cytoplasmic adaptor molecule, has been shown to link cell surface receptors to downstream signal transduction, especially the ERK, Wnt/β-catenin and TGF-β signaling pathway." (PMID 27036032, 2016). "The tumor suppressor functions of Dab2 have been attributed to its roles in suppressing Ras/MAPK signaling, epithelial organization, and cell adhesion/migration." (PMID 27933291, 2016). "Probably, the activity as a negative regulator of the Ras/MAPK pathway contributes to the tumor suppressor activity of Dab2 as well." (PMID 27933291, 2016). "In this first systematic review, Dab2 expression was analyzed in approximately 789 human tumor and 432 normal tissues of 15 included papers." (PMID 24772157, 2014). "Dab2 is a putative tumor suppressor gene, but modulates late stages of tumor progression by promoting EMT-dependent metastasis." (PMID 23715860, 2013). "Since its expression is lost in several cancer types, Dab2 has been suggested to be a tumor suppressor." (PMID 24168030, 2013). "DAB2 is a tumor suppressor and interacts with DAB2 interacting protein (DAB2IP, DIP1/2, AIP1) in a manner that enhances its tumor suppressing activity." (PMID 23382857, 2013). "DAB2 (disabled homolog 2), a protein of clathrin coated pits, is a negative regulator of the Wnt/β-catenin pathway and therefore a putative tumor suppressor." (PMID 23213280, 2012). "In the most advanced tumours, Dab2 (glomerulosa) and Akr1b7 (fasciculata) were virtually undetectable, indicating loss of functional differentiation." (PMID 22952916, 2012). "Epigenetic downregulation of human disabled homolog 2 (DAB2) also switches TGFβ from a tumor suppressor to a tumor promoter in head and neck carcinomas." (PMID 27340590, 2012). "Previously, DAB2 has been found to exert the tumour suppressor effect by uncoupling MAP kinase activation and c-Fos expression." (PMID 20525238, 2010). "Ectopic expression of DAB2 reduced in vitro tumour growth in ovarian, prostatic and choriocarcinoma cell lines and significantly reduced the ability to form tumours in nude mice when stably expressed in ovarian cancer cells." (PMID 20525238, 2010). "To evaluate the potential tumour suppressor effect of DAB2 in NPC, we transfected full length DAB2 cDNA in pcDNA3.1(+) expression vector into C666-1 cells." (PMID 20525238, 2010). "DAB2 is a putative tumour suppressor and plays an important regulatory role in cellular differentiation." (PMID 20525238, 2010). "Aberrant methylation on the promoter region of DAB2 was detected in 65.2% (30/46) of NPC primary tumour biopsy samples." (PMID 20525238, 2010). "Disabled-2 (Dab2) or deleted in ovarian carcinoma-2 is a putative tumour suppressor first identified in a screen for transcripts downregulated in ovarian tumours vs normal ovarian surface epithelial cells." (PMID 21063401, 2010). "Similarly, CD36 and DAB2, when carried by EVs, contribute to lipid uptake and signal transduction within the tumor stroma." (PMID 40565366, 2025). "Originally identified in ovarian tumors, DAB2 has also been detected in various other tumor types." (PMID 38613672, 2024).
tumor (continued). "The interaction between FAP+ CAFs and DAB2+ TAMs may be important for the formation of the capsule at the tumor border." (PMID 39239526, 2024). "DAB2 expression is suppressed by promoter hypermethylation in multiple tumor types while SCFAs may reduce promoter methylation by suppressing the expression of several DNMTs." (PMID 37432606, 2023). "This is consistent with the previously proposed role of DAB2 as a tumor suppressor." (PMID 37510211, 2023). "Also, significant alterations in genes associated with tumor cell invasion were detected, such as significant upregulation of TGFβ1, ROAR, DAB2, BMP6, NOS2, PLXN2, and CADPS exhibited, and significant downregulation of TCF4." (PMID 38003292, 2023). "Moreover, already mentioned role of DAB2 in TGF β signaling has important potential as a tumor suppressor." (PMID 37510211, 2023). "Furthermore, the overexpression of DAB2 eliminated the effectiveness of dendritic cell vaccines in the context of dendritic cell-relevant tumor immunotherapy." (PMID 37693905, 2023). "Additionally, disabled 2 mitogens responsive phosphoprotein (DAB2) is highly expressed in TAMs, which in turn accelerates tumor cell invasion through an integrin-ECM interaction." (PMID 37479694, 2023). "Concerning all mentioned roles, DAB2 was intensely investigated as a potential tumor suppressor." (PMID 37510211, 2023). "The extent of tumor growth inhibition was comparable to Dab2-edited BMDMs." (PMID 37388918, 2023). "Furthermore, we found a significant increase in DAB2+, CD68+ and DAB2+ CD68+ cells in tumor associated stroma of metastatic HGSOC compared to matched primary tissues." (PMID 37815603, 2023). "The loss of DAB2 is associated with activation of key signalling pathways including Wnt, MAPK and TGFβ which is associated with enhanced cell proliferation, chemotherapy resistance and tumour progression, supporting its role as a tumour suppressor." (PMID 36614139, 2022). "Recent research suggests DAB2 has tumour promoting effects in the tumour microenvironment (TME)." (PMID 36614139, 2022). "A greater understanding of the functional role of DAB2 in the TME may lead to the development of novel strategies to block tumour progression." (PMID 36614139, 2022). "DOC2/DAB2 interaction protein (DAB2IP; also known as apoptosis signal‐regulating kinase 1‐interacting protein‐1 [AIP1]) directly interacts with DOC‐2/DAB2 to regulate various pathological characteristics of tumour cells, such as proliferation, invasion and apoptosis." (PMID 33166004, 2021). "Dab2 is expressed in different carcinomas and characterized as a tumor suppressor." (PMID 32607799, 2020). "UC cell lines in this study expressed mainly p96-DAB2 but depending on cancer types and cell lines, DAB2 expression isoforms and the location of expression differ, which is presumed to result in the difference of tumor promotion or suppression." (PMID 31968685, 2020). "Two other groups have also described that DAB2 promotes tumor cell migration." (PMID 31968685, 2020). "Inhibiting the role of DAB2 can lead to tumor shrinkage and suppression of invasion, which may help improve the prognosis of UCB in clinical practice." (PMID 31968685, 2020). "Disabled-2 (Dab2) is known as a tumor suppressor as well as a Wnt pathway inhibitor." (PMID 30547821, 2018). "Disabled-2 (DAB2) is a crucial tumor suppressor, but its roles in ESCCs are uncertain." (PMID 27036032, 2016). "Nevertheless, tumor incidence is relatively low (about 10%) and likely loss of Dab2 contributes but is not sufficiently to cause tumorigenesis." (PMID 27933291, 2016). "Accordingly, DAB2 shall carry on a dual-role manner during tumor progression." (PMID 27036032, 2016). "We investigated whether low DAB2 expression in ESCCs could lead into tumor progression and poor prognosis." (PMID 27036032, 2016). "Dab2 is also considered a tumor suppressor and lost in several malignant cancers." (PMID 26681200, 2015).